ROR1 (ROR family WNT receptor 1)
Diseases named in the same sentence as ROR1 in open-access papers (continued):
Sharing a sentence is not in itself a finding about the gene and the disease.
cancer (continued). "With the growth of the ID8 cell-transplantable EOC being suppressed, the cytotoxic activities of splenocytes, NK cells, and CDC as well as serum anti ROR-1 antibody and IFN-γ levels were increased in the ID8 cancer stem-like cell-vaccinated mice, suggesting elicit effective immunity against EOC." (PMID 31008116, 2019). "In vivo administration of anti-ROR1 specific antibody, D10 revokes the potentiating effect of ROR1 on TCL1-tg cells, suggesting that this may be a novel therapeutic target in ROR1-expressing cancers." (PMID 26821067, 2016). "We found that AKT was activated in cancer cells that expressed ROR1, but not in cells that were silenced for ROR1." (PMID 22403610, 2012). "In this study, our attempts to detect the endogenous Ror1 expression using rat-anti Ror1 antibody showed a small truncated form of Ror1 (~40 kD) in several cancer cell lines (data not shown)." (PMID 20587074, 2010). "Additionally, ROR1 is likely to have superior endocytic activity in comparison with HER2, potentially enhancing the efficacy of ROR1-targeting conjugates in the delivery of PROTAC to cancer cells." (PMID 39816690, 2025). "Receptor tyrosine kinase-like orphan receptor 1 (ROR1) is an attractive therapeutic target due to its high expression on malignant B-cells and minimal presence in normal adult tissues, allowing the development of more potent and safer drugs for cancer treatment." (PMID 41479906, 2025). "Importantly, ROR1 is detectable in embryonic tissue and generally absent in adult tissue, nominating it as an ideal anti-cancer drug target." (PMID 37202777, 2023). "Cancer cells may express ROR1 or ROR2 at levels not observed in normal post-partem tissues and, therefore, the protein antigens encoded by these genes could serve as potential targets for therapy." (PMID 37029329, 2023). "Moreover, ROR1 interacts with SRC, a key regulator of cancer cells." (PMID 36297673, 2022). "With ROR1-targeted therapy already showing promising signs of activity in various cancer types, KAN0441571C brings the added benefits of being a small molecule inhibitor that directly inhibits the tyrosine kinase domain of a selectively overexpressed kinase, ROR1." (PMID 34088900, 2021). "In addition, there are some interactions of Fzd receptors and/or ROR1/2 (receptor tyrosine kinase-like orphan receptor 1/2) with non-canonical Wnt ligands in Wnt-dependent cancer progression." (PMID 29335534, 2018). "Furthermore, as an oncofetal protein with absence of expression in most adult tissue, ROR1 represents an ideal druggable target for cancer therapy." (PMID 24752542, 2014). "Importantly, ROR1 is only detectable in embryonic tissue and generally absent in adult tissue, making the protein an ideal drug target for cancer therapy." (PMID 24752542, 2014). "However, PGG has not been validated as an ROR1 inhibitor in any in vitro or in vivo cancer studies." (PMID 39000112, 2024). "We therefore concluded a stimulatory effect of EV-associated ROR1 and ROR2 on cancer cell invasion requiring the presence of RhoA without significantly upregulating its expression.We next analyzed whether EV uptake was required for the invasion-promoting effect of ROR-EVs." (PMID 37430307, 2023). "Thus, our result documenting a potent antitumor effect of PTK7-CAR T cells adds PTK7 to the kind list of ROR1, which, as a member of Wnt signaling-related pseudokinases, had a characteristic enriched expression in TIC/CSCs and is suitable as a potential therapeutic target for cancer immunotherapy." (PMID 34475869, 2021). "Thus, two different studies showed the induction of ROR1 (type 1 receptor tyrosine kinase-like orphan receptor) following treatment with trastuzumab emtansine or chemotherapy: ROR1 enhanced the expression of YAP/TAZ and the self-renewal of cancer stem cells, inducing therapeutic resistance." (PMID 32210163, 2020). "However, it was not known whether other cancers expressed ROR1 or whether its expression had functional and clinical significance." (PMID 22403610, 2012).
cancer (continued). "Moreover, the expression of ROR1 by cancer cells has been associated with enhanced cancer cell migration, epithelial–mesenchymal transition (EMT), increased risks of relapse and/or metastasis, and an unfavorable prognosis relative to that of cancers that do not express ROR1." (PMID 39062146, 2024). "For instance, the therapeutic relevance of targeting the non-canonical Wnt receptors ROR1 and ROR2 (receptor tyrosine kinase-like orphan receptor) has been investigated in numerous cancers of both hematological and epithelial origin." (PMID 37400436, 2023). "The induction of apoptosis with ROR1 knockdown, EGFR signaling potentiation and ROR1-mediated upregulation of EMT genes support the notion that ROR1 plays an important role in cancer progression rather than just a bystander." (PMID 24752542, 2014). "Accordingly, they reasoned that cancer cells expressing predominately ROR1V3 relative to ROR1 would predominately express cytoplasmic, and not surface, ROR1 that could react with anti-ROR1 mAbs by IHC." (PMID 39062146, 2024). "In addition, ROR1 showed a moderate negative correlation with activated CD4+, neutrophils, and natural killer T (NKT) cells in a few cancer types." (PMID 34319035, 2021).
hematological malignancies (19 papers, 2014 to 2025). "Because immunosuppression and hematologic malignancies are established risk factors for cSCC and ROR1 is known to be overexpressed in several hematologic neoplasms, we additionally assessed whether ROR1 expression was enriched in patients with hematologic malignancies." (PMID 41355329, 2025). "Zilovertamab vedotin is a humanized IgG1 monoclonal antibody directed against ROR1, associated with a proteolytically cleavable linker and the antimicrotubule agent monomethyl auristatin E. The transmembrane protein ROR1 has been found overexpressed in several hematologic malignancies." (PMID 38790939, 2024). "In various hematologic malignancies the receptor tyrosine kinase‐like orphan receptor 1 (ROR1) has been described to be overexpressed and targeting of ROR1 is a promising treatment option currently tested in clinical trials." (PMID 41355329, 2025). "In the phase I first-in-human study in hematologic malignancies (waveLINE-001), the ROR1-targeting antibody–drug conjugate zilovertamab vedotin showed promising activity and manageable safety in R/R DLBC." (PMID 38790939, 2024). "It synthetizes the existing literature, and gathers results on ROR1-targeted therapies, representing a significant step forward in expanding immunotherapies for hematological malignancies." (PMID 39551787, 2024). "In meta-analyses, high ROR1 expression was found to relate to worse overall survival in hematologic malignancies and solid tumors." (PMID 37111634, 2023). "Overexpression of ROR1 has not only been reported in hematological malignancies, but has also gained increasing attention in solid tumors." (PMID 33445713, 2021). "The involvement of ROR1 in tumorigenesis of many solid tumors and hematological malignancies has already been documented 23,24,27,31." (PMID 32695279, 2020). "As ROR1 could be targeted in solid tumors and hematological diseases it could represent a target for oncological conditions as well as for MM." (PMID 39551787, 2024). "ROR1 has emerged as a promising target in hematological malignancies." (PMID 39551787, 2024). "In hematological malignancies, the use of CAR T cell therapies and BiTEs targeting ROR1 is an emerging research area." (PMID 39551787, 2024). "These efforts and the promising preclinical data led to the implementation of a phase I study with ROR1 CAR T cells (NCT02706392), which does not only include patients with hematological malignancies, but also solid tumors." (PMID 33445713, 2021). "ROR1 IR was slightly higher in patients with hematologic malignancies compared with those without (1.09 ± 0.60 vs. 0.99 ± 0.56)." (PMID 41355329, 2025). "Receptor tyrosine kinase ROR1, an embryonic protein involved in organogenesis, is expressed in certain hematological malignancies and solid tumors, but is generally absent in adult tissues." (PMID 25978653, 2015).
hematological cancers (7 papers, 2019 to 2025). "It was reported that ROR1 is involved in the development of many solid and hematological tumor cells." (PMID 39551787, 2024). "Clinical trials also evaluated the ADC VLS-101 and anti-ROR1 CAR-T cells for the treatment of hematological cancers." (PMID 38773263, 2024). "Other studies also underscore that anti-ROR1 mAb treatment enhanced venetoclax activity in CLL and MCL, suggesting that, in ROR1-positive hematological cancers, this approach represents a promising strategy." (PMID 32751131, 2020).
lung (3 papers, 2016 to 2025). "We analyzed ROR1 expression by quantitative real-time PCR (qRT-PCR) in 56 histologically confirmed lung AC, stage I to IV, in addition we evaluated its association with TTF-1 (thyroid transcription factor-1) expression and the main molecular alterations involved in lung cancerogenesis." (PMID 33172431, 2020). "On the other hand, the specific expression of ROR1 in lung ADC tissues made it a potential target for lung ADC therapy, thus we are currently developing novel small-molecule agents and monoclonal antibodies against ROR1 to treat lung ADC patients." (PMID 27830754, 2016).
infection (2 papers, 2010 to 2021). The state of being infected such as from the introduction of a foreign agent such as serum, vaccine, antigenic substance or organism. "Infection with STAT3-shRNA reduced the mRNA levels of ROR1 and the Stat3-regulated genes STAT3, Bcl2, Bcl-XL, Cyclin D1, c-Myc, WAF1/p21, and Pim1." (PMID 20686606, 2010). "Knockdown of noncanonical pathway coreceptors ROR1 and ROR2 resulted in impaired infection as well, although to a lesser degree." (PMID 33883266, 2021).
adenocarcinoma (1 paper, 2023). A common cancer characterized by the presence of malignant glandular cells. "There was also a trend towards shorter TTP in ROR1+ adenocarcinoma NSCLC patients compared to ROR1− patients." (PMID 37111634, 2023). "In adenocarcinoma, no statistical association between ROR1 expression and age, grading, smoking status, and overall survival was seen." (PMID 37111634, 2023).
metabolic disease (1 paper, 2022). A congenital disorder (due to inherited enzyme abnormality) or acquired (due to failure of a metabolically important organ) disorder resulting from an abnormal metabolic process. "Decreased gene body methylation within ROR1 may indicate decreased expression of ROR1, subsequently promoting increased adipogenesis in those with low HDL-Cholesterol levels, affecting susceptibility to later life metabolic disease." (PMID 35000590, 2022).
ROR1 also shares sentences with these, for which no sentence is quoted: embryonal rhabdomyosarcoma (3 papers); fibrosarcoma (3); marginal zone lymphoma (3); Alzheimer disease (2); breast ductal carcinoma (2); diabetes (2); myeloid malignancies (2); rhabdomyosarcoma (2); Anaplastic Thyroid Carcinoma (1); atherosclerosis (1); bladder tumors (1); brain tumor (1); cataract (1); clear cell carcinomas (1); CNS tumors (1); cutaneous squamous cell carcinoma (1); endometrioid uterine carcinoma (1); hearing loss (1); hematologic neoplasms (1); Infertility (1); influenza infection (1); intestinal tumors (1); ischemic heart disease (1); leiomyosarcoma (1); Lymph Node (1); medulloblastoma (1); mesenchymal chondrosarcoma (1); metabolic syndrome (1); metastatic prostate carcinoma (1); mucinous adenocarcinoma (1).
A further 18 diseases each share a sentence with ROR1 in 1 paper.